GNG2 (G protein subunit gamma 2)
Description:
Guanine nucleotide-binding proteins (G proteins) are involved as a modulator or transducer in various transmembrane signaling systems. The beta and gamma chains are required for the GTPase activity, for replacement of GDP by GTP, and for G protein-effector interaction.
Synonyms: HG3F1
Tractability: Small molecule: a structure with a bound ligand is known; a high-quality ligand is known. Antibody: UniProt places it where antibodies can reach, with high confidence; its Gene Ontology location is reachable by antibodies, with high confidence; the Human Protein Atlas places it where antibodies can reach. PROTAC: ubiquitination databases record sites on it; its protein half-life has been measured; a small molecule that binds it is known.
Gene: Protein-coding gene on chromosome 14 (51,826,195 to 51,979,342, forward strand). Ensembl gene ENSG00000186469.
Subcellular location: Cell membrane
Subcellular location (Human Protein Atlas): Plasma membrane; Vesicles
Pathways (Reactome):
Signal Transduction: Ca2+ pathway; Extra-nuclear estrogen signaling; G alpha (12/13) signalling events; G alpha (i) signalling events; G alpha (q) signalling events; G alpha (s) signalling events; G alpha (z) signalling events; G beta:gamma signalling through BTK; G beta:gamma signalling through CDC42; G beta:gamma signalling through PI3Kgamma; G beta:gamma signalling through PLC beta; G-protein activation; GPER1 signaling; Glucagon-type ligand receptors
Hemostasis: ADP signalling through P2Y purinoceptor 1; ADP signalling through P2Y purinoceptor 12; Prostacyclin signalling through prostacyclin receptor; Thrombin signalling through proteinase activated receptors (PARs); Thromboxane signalling through TP receptor
Metabolism: Adrenaline,noradrenaline inhibits insulin secretion; Glucagon signaling in metabolic regulation; Glucagon-like Peptide-1 (GLP1) regulates insulin secretion
Neuronal System: Activation of G protein gated Potassium channels; Inhibition of voltage gated Ca2+ channels via Gbeta/gamma subunits; Presynaptic function of Kainate receptors
Cellular responses to stimuli: High laminar flow shear stress activates signaling by PIEZO1 and PECAM1:CDH5:KDR in endothelial cells
Disease: ADORA2B mediated anti-inflammatory cytokines production
Metabolism of proteins: Cooperation of PDCL (PhLP1) and TRiC/CCT in G-protein beta folding
Transport of small molecules: Vasopressin regulates renal water homeostasis via Aquaporins
Gene Ontology:
Molecular function: G-protein beta-subunit binding; protein binding
Biological process: adenylate cyclase-activating dopamine receptor signaling pathway; cellular response to catecholamine stimulus; cellular response to prostaglandin E stimulus; G protein-coupled receptor signaling pathway
Cellular component: extracellular exosome; heterotrimeric G-protein complex; membrane; plasma membrane; synapse
Genetic constraint (gnomAD): Loss-of-function variants: 1 observed, 3.14 expected, observed/expected ratio (o/e) 0.32, 90% interval 0.11 to 1.42. That is too few expected variants to judge how well the gene tolerates losing a copy. Missense variants: 43 observed, 66.5 expected, observed/expected ratio (o/e) 0.65, 90% interval 0.51 to 0.83. Synonymous variants: 20 observed, 24.37 expected, observed/expected ratio (o/e) 0.82, 90% interval 0.58 to 1.19.
Homologues: Orthologues: chimpanzee GNG2 (100% identical), dog GNG2 (100% identical), guinea pig GNG2 (100% identical), mouse Gng2 (100% identical), tropical clawed frog gng2 (100% identical), rat Gng2 (99% identical), zebrafish gng2 (94% identical). Paralogues in human: GNG3 (76% identical), GNG4 (76% identical), GNG8 (69% identical), GNG7 (68% identical), GNG12 (61% identical), GNG10 (48% identical), GNG5 (46% identical), GNG5B (44% identical), GNGT2 (39% identical), GNG11 (32% identical), GNGT1 (32% identical).
Diseases named in the same sentence as GNG2 in open-access papers:
GNG2 is named in the same sentence as 26 diseases in open-access papers, as found by Europe PMC text mining. Sharing a sentence is not in itself a finding about the gene and the disease. The quoted sentences say what the papers report.
malignant melanoma (8 papers, 2016 to 2025). "GNG2, G Protein Subunit Gamma 2, implicated as a tumor suppressor in melanomas and breast cancer, was also upregulated in response to treatment." (PMID 41262902, 2025). "GNG2 is a part of the heterotrimeric G-protein gamma subunit and can inhibit the occurrence and development of human malignant melanoma." (PMID 35322009, 2022). "As a part of heterotrimeric G protein, GNG2 independently inhibits the proliferation and invasion of human malignant melanoma cells." (PMID 35322009, 2022). "The proliferation of SK-Mel28 human malignant melanoma cells was suppressed with overexpressed GNG2, and the mean tumor size of overexpressed-GNG2 SK-Mel28 cells was less than that of the controlled SK-Mel28 cells in nude mice after inoculation." (PMID 34222011, 2021). "Although it was reported that the overexpression of GNG2 inhibits the migration and invasiveness of melanoma cells, little is known about the function of GNG2 in PDAC or in other tumor types." (PMID 27414409, 2016). "Previous studies mainly focused on functional analysis of GNG2 in human malignant melanoma cells." (PMID 33922375, 2021). "Although previous studies confirmed the down-expression of GNG2 in malignant melanoma and pancreatic ductal adenocarcinoma (PDAC) cancers, there has been no discussion so far about the role of GNG2 in breast cancer and its metastasis to the brain." (PMID 35045088, 2022).
breast carcinoma (5 papers, 2022 to 2025). "Interestingly, we found that the down-expression of GNG2 is associated with breast cancer metastasis to the brain." (PMID 35045088, 2022). "The interaction between GNG2 and the muscle RAS oncogene homolog may inhibit the activity of Akt and ERK, thereby suppressing the proliferation of estrogen-dependent breast cancer cells." (PMID 41174058, 2025).
aortic aneurysm (1 paper, 2021). A ruptured aneurysm located in the wall of the proximal portion of the descending aorta proceeding from the arch of the aorta. "The biological relevance of FRMD6, GNG2 and MBP with respect to the development of aortic aneurysms is unclear at this time." (PMID 34469433, 2021).
atrial fibrillation (1 paper, 2021). A disorder characterized by an electrocardiographic finding of a supraventricular arrhythmia characterized by the replacement of consistent P waves by rapid oscillations or fibrillatory waves that vary in size, shape and timing and are accompanied by an irregular ventricular response. "The protein-protein interaction network revealed that EGFR, GNG2, and FPR2 were related to atrial fibrillation." (PMID 34938350, 2021). "The PPI network analysis illustrated that the hub genes related to atrial fibrillation are EGFR, GNG2, and FPR2." (PMID 34938350, 2021). "And bioinformatics analysis of upregulated genes indicates that pathway endodermal cell differentiation and key genes EGFR, GNG2, and FPR2 are related to atrial fibrillation." (PMID 34938350, 2021). "We could conclude that EGFR, GNG2, and FPR2 were the most closely related to patients with atrial fibrillation." (PMID 34938350, 2021).
cervical cancer (1 paper, 2021). A primary or metastatic malignant neoplasm involving the cervix. "The highly expressed GNG2 may also be associated with the down-regulation of miR-23b-3p (0.223-fold change, p < 0.001), which was identified to be associated with various cancers, such as cervical cancer, renal cancer and pancreatic cancer." (PMID 33922375, 2021).
cervical squamous cell carcinoma (1 paper, 2022). A squamous cell carcinoma arising from the cervical epithelium. "GNG2 expression was downregulated in multiple cancers, including BC, cervical squamous cell carcinoma (CESC), and colonic adenocarcinoma (COAD)." (PMID 35322009, 2022).
colorectal cancer (1 paper, 2021). A primary or metastatic malignant neoplasm that affects the colon or rectum. "We found that there were intensive protein-protein interaction pairs, and 3 potential hub genes (POLR2B, GNB2, and GNG2) were identified, which suggested that universal recurrence associated genes may cooperate together to have an impact on the recurrence of stage II colorectal cancer patients." (PMID 33628243, 2021).
endometrial cancer (1 paper, 2025). Primary or metastatic malignant neoplasm involving the endometrium (mucous membrane that lines the endometrial cavity). "Kaplan Meier plots using TCGA Endometrial Cancer database revealed that high mRNA expression of SCGB1D2, CD52, GNG2, GDNF, and SCUBE1correlated with favorable prognosis in EC patients (n=547)." (PMID 41262902, 2025).
pulmonary hypertension (1 paper, 2022). Increased pressure within the pulmonary circulation due to lung or heart disorder. "The avoidance of pulmonary hypertension is due to the increased expression of GNG2 and CA2 and the decreased expression of TAGLN and MPO, and the increased vascular permeability is due to the increased expression of GNG2 and the decreased expression of GSN." (PMID 36009723, 2022).
thyroid carcinoma (1 paper, 2025). "In thyroid carcinoma, KCNJ2 inhibits proliferation, migration, and EMT progression of papillary cells by upregulating GNG2 expression." (PMID 40314029, 2025).
triple-negative breast carcinoma (1 paper, 2022). An invasive breast carcinoma which is negative for expression of estrogen receptor (ER), progesterone receptor (PR), and human epidermal growth factor receptor 2 (HER2). "Cox regression analysis showed that GNG2 was independently associated with overall survival in patients with luminal A and triple-negative breast cancers (TNBC)." (PMID 35322009, 2022).
tumor (10 papers, 2016 to 2025). "Genes with reported anti-tumor functions, including SCGB1D2 (Secretoglobin Family 1D Member 2, lipophilin B), FKBP5, CD52, DLK1, GALNT9, GNG2, GDNF, and TMEM35A, were significantly upregulated after CUDC-907 + MPA treatment and validated by RT-PCR." (PMID 41262902, 2025). "Additional molecular mediators, including GNG2, a tumor suppressor limiting brain metastasis and FSTL3, which promotes tumor progression via HIF1α-dependent pathways, have emerged as actionable biomarkers for metastatic control." (PMID 41403952, 2025). "We further used DAVID to search for those genes from the predicted target genes that are related to tumor, and found the target genes of LYN, RASAL2, FZD4, and GNG2 for further study." (PMID 35174106, 2022). "On the contrary, CM-272 increased levels of genes related to tumor growth suppression: CPA4 (Carboxypeptidase A4), a negative regulator of the AKT/c-MYC pathway in NSCLC and GNG2 (G-protein gamma subunit 2), which impairs AKT phosphorylation and cell survival." (PMID 39488528, 2024).
cancer (8 papers, 2019 to 2024). A tumor composed of atypical neoplastic, often pleomorphic cells that invade other tissues. "We found that four genes (EPHA3, PDGFB, PDGFRB, and GNG2) are implicated in cancer cell migration, invasion, and angiogenesis." (PMID 38233802, 2024). "For example, the following top 100 MDS genes can be mentioned that are not yet covered by approved or experimental cancer or antineoplastic drugs [according to DrugBank, DGIdb, FDA6, HMDB, Tocris7, GeneCards databases]: GRB2, SOS1,SOS2, SHC1, GNB1, CREB1, GNG2, GNAQ, GNB5, GNAI2." (PMID 30728774, 2019).
infection (2 papers, 2017 to 2021). The state of being infected such as from the introduction of a foreign agent such as serum, vaccine, antigenic substance or organism. "However, there is no direct evidence to prove the association between the up-regulation of GNG2 and the infection of S. aureus in mammary glands." (PMID 33922375, 2021). "Various repressors of apoptosis such as Ilf3, Zmym2, Satb1, Ccl21 and Scd were downregulated and expression levels of inducers of apoptosis such as Daxx, Oas1, Lcn2 and Gng2 were upregulated with V3000 infection at 24 h pi resulting in an overall activation of the apoptotic pathway." (PMID 28446152, 2017).
GNG2 also shares sentences with these, for which no sentence is quoted: papillary thyroid carcinoma (2 papers); Bovine mastitis (1); brain tumours (1); colonic adenocarcinoma (1); diabetes (1); Huntington disease (1); lung carcinoma (1); lymphoma (1); neurodevelopmental disorder (1); pancreatic cancer (1); pancreatic ductal adenocarcinoma (1); renal carcinoma (1).